MTOR (mechanistic target of rapamycin kinase)
Diseases named in the same sentence as MTOR in open-access papers (continued):
Sharing a sentence is not in itself a finding about the gene and the disease.
ovarian carcinoma (continued). "Thus, the strategy of combining Pae with an autophagy inhibitor to block Akt/mTOR-dependent autophagy could enhance the antitumour activity of Pae and warrants further application for the treatment of ovarian cancer." (PMID 31406198, 2019). "Interestingly, recent research has linked the PIM kinases to the PI3K/AKT/mTOR pathway in several types of cancers, but their connection in ovarian cancer has not been studied yet." (PMID 29401696, 2018). "Therefore, the PI3K/AKT/mTOR pathway may have been more strongly activated by milk (casein) intake than plant protein (soy protein) intake in our mice with ovarian cancer." (PMID 29844867, 2018). "Therefore, mTOR represents potentially important therapeutic target for ovarian cancer." (PMID 28938571, 2017). "Therefore, sunitinib may act directly on tumour cells to inhibit mccRCC growth, consistent with results in ovarian cancer that VEGF stimulates the mTOR pathway." (PMID 28648142, 2017). "We determined whether mTOR inhibition could interfere with TNT formation in ovarian cancer cells." (PMID 27223082, 2016). "Thus, targeting the PI3K/AKT/mTOR pathway could have a potential role in the treatment of ovarian cancer, particularly for tumors in obese women." (PMID 26959121, 2016). "In addition, PI3K and Akt inhibitors, acting upstream of mTOR inhibitors, are in clinical development for the treatment of ovarian cancer and may have the potential to more effectively disrupt this pathway." (PMID 27983698, 2016). "Importantly, we found that combinatorial inhibition of IKKβ and PI3K/mTOR could effectively abolish clonogenic growth of ovarian cancer cells compared with individual inhibition." (PMID 26657155, 2016). "By analyzing the expression levels of miR-497, mTOR and p70S6K1 in a clinical gene-expression array dataset, we found that mTOR and p70S6K1, two proteins correlated to chemotherapy-resistance in multiple types of human cancers, were inversely correlated with miR-497 levels in ovarian cancer tissues." (PMID 26238185, 2015). "To further test the physiological relevance of mTOR/p70S6K1 and miR-497 interaction, we performed in silico analysis for miR-497 and mTOR/p70S6K1 expression from The Cancer Genome Atlas (TCGA) 2011 dataset for Ovarian Cancer, comprising of 489 patient samples with follow-up information." (PMID 26238185, 2015). "Therefore, we hypothesize that therapies targeting mTOR activity should be effective against ovarian cancer, particularly in obese patients." (PMID 26053184, 2015). "In addition, the anti-proliferative and anti-angiogenic effects of thioridazine on ovarian carcinoma cells might be caused by inhibition of the PI3K/Akt and FAK/ mammalian target of rapamycin (mTOR) pathways in vitro." (PMID 24952635, 2014). "Thus, stimulation of the EGF receptor in CCA, which may be directly associated with the progression of ovarian cancer, can potentiate the PI3K/Akt/mTOR pathway." (PMID 23819061, 2013). "Studies in cervical and ovarian cancers revealed that activation of the PI3K/Akt/mTOR pathway is associated with resistance to microtubule-targeting agents, implicating a potential benefit of combined targeting of both the microtubules and the PI3K/Akt/mTOR pathway." (PMID 23509629, 2013). "Moreover, rapamycin treatment significantly increased the protein levels of E-cadherin and markedly diminished the suppressive effect of FGF2 on E-cadherin protein levels, indicating that the PI3K/Akt/mTOR pathway is involved in FGF2-induced E-cadherin suppression in ovarian cancer cells." (PMID 23554977, 2013). "Therefore, the molecular targeting of multiple signaling pathways such as EGFR, VEGFR, HIF-1, and PI3K/PTEN/AKT/mTOR may improve responses in recurrent and resistant ovarian cancers." (PMID 22481932, 2012).
ovarian carcinoma (continued). "mTOR inhibitors might have the potential of avoiding these problems Taking our data into consideration, suggestive of an autocrine VEGF-A loop through the AKT/mTOR signalling pathway, this adds preclinical rationale for mTOR inhibition in the management of ovarian cancer." (PMID 19240722, 2009). "Curcumin has been demonstrated in ovarian cancer cell lines and murine models to influence chemosensitization, hindering NF‐κB, Wnt/β‐catenin, AKT/mTOR/p70S6K pathways and reducing the expression of P‐glycoprotein to restore ovarian cancer drug sensitivity." (PMID 40968783, 2026). "Inhibition of CRM1-mediated nuclear export has been demonstrated to enhance the accumulation of mTOR in the nucleus, resulting in decreased protein levels of mTOR and its downstream targets, STAT3 and MMP9, in ovarian cancer cells." (PMID 41578763, 2025). "The results demonstrate that GA significantly inhibits the proliferation of ovarian cancer cells and enhances the anticancer effects of DDP by regulating the PI3K/AKT/mTOR signaling pathway." (PMID 41059296, 2025). "Signal pathway inhibitors have garnered significant attention in ovarian cancer research, particularly those targeting the PI3K/AKT/mTOR pathway." (PMID 40395324, 2025). "In ovarian cancer, MDSC-derived PGE2 increases cancer stem-like cell properties and PD-L1 expression through the mammalian target of rapamycin (mTOR) pathway." (PMID 39990210, 2025). "In ovarian cancers, including HGSOC, the PI3K/AKT/mTOR pathway is frequently hyperactivated through various genetic alterations, driving cell proliferation, migration, and chemotherapy resistance." (PMID 40429728, 2025). "This article summarizes available information on the effects of pentacyclic triterpenoids on the PI3K/AKT/mTOR, MAPK/ERK, NF-κB, JAK/STAT, Notch, HIF-1α, TGF-β, Wnt/β-catenin, Hippo, and Hedgehog signaling pathways in ovarian cancer cells." (PMID 41373772, 2025). "In ovarian cancer, SHCBP1 overexpression induces cisplatin resistance by activating AKT/mTOR signaling and inhibiting autophagic cell death." (PMID 41009347, 2025). "Therefore, downregulating AGPAT3 expression or blocking its enzymatic product, phosphatidic acid, from binding to mTOR might be considered therapeutic approaches to overcome cisplatin chemoresistance in ovarian cancer, which has fewer side effects than other classes of mTOR inhibitors do." (PMID 40063560, 2025). "In ovarian cancer, cardamonin suppresses M2 polarization and reduces TAM-mediated tumor support by inhibiting the mTOR signaling pathway and STAT3 activation." (PMID 40330466, 2025). "This review contains the evolution of PI3K and mTOR drugs that are approved by the FDA and are in the trials for different cancer types, including ovarian cancer." (PMID 38584538, 2025). "In ovarian cancer cells, it has been demonstrated that fibroblast growth factor (FGF2) results in increased expression of SLUG and ZEB1 by activating the PI3K/AKT/mTOR and MAPK/ERK signaling pathways." (PMID 40678416, 2025). "GALNT14 has emerged as a key regulator of both ferroptosis and apoptosis in ovarian cancer through its effects on epidermal growth factor receptor (EGFR) glycosylation and downstream mTOR pathway activation." (PMID 41008983, 2025). "Inhibition of the PI3K/Akt/mTOR and ERK1/2 signaling pathways has been shown to reduce progranulin (PGRN) expression in ovarian cancer cells, suggesting a potential strategy to overcome chemoresistance in OCCC." (PMID 41383608, 2025). "One key pathway implicated in drug resistance across various gynecological malignancies, including EC, cervical cancer, and ovarian cancer, is the PI3K/Akt/mTOR signaling pathway." (PMID 41378297, 2025).
ovarian carcinoma (continued). "This study evaluated the anti-tumor effects of CBD, THC, and their combination on SKOV3 and A2780 ovarian cancer cells, focusing on phosphorylation-dependent regulation of the PI3K/AKT/mTOR pathway." (PMID 41472794, 2025). "Tetrahydroxycurcumin can also cause apoptosis and prevent autophagic cell death in the human ovarian cancer cell lines A2780 and SK‐OV‐3 by modifying the AKT/mTOR/p70S6K pathway." (PMID 41179371, 2025). "The clinical relevance of GALNT14 in chemotherapy resistance has been demonstrated in cisplatin-resistant ovarian cancer models, in which combination therapy targeting both GALNT14 and mTOR signaling promoted cell death." (PMID 41008983, 2025). "In summary, the PI3K/AKT/mTOR pathway is a critical target in ovarian cancer therapy, and the combination of PI3K inhibitors with PARP inhibitors shows promise in some ovarian cancer patients." (PMID 40395324, 2025). "In cisplatin-resistant ovarian cancer cells, m7G modification significantly enhances translation of EGFR pathway genes and activates PI3K/AKT/mTOR signaling, which reduces apoptosis sensitivity." (PMID 40895564, 2025). "Pharmacological inhibition of mTOR results in upregulation of DYRK1B abundance in PDAC and ovarian cancer cells." (PMID 39863750, 2025). "This study investigates the antitumor effects of gallic acid (GA) on ovarian cancer cells and its potential synergistic therapeutic effects with cisplatin (DDP) through modulation of the PI3K/AKT/mTOR signaling pathway." (PMID 41059296, 2025). "For example, the IncRNA HCG11, a non-coding RNA, appears to suppress AKT/mTOR-mediated cell growth in ovarian cancer via the upregulation of PTEN activity, suggestive of an epigenetic modulation of mTOR." (PMID 38893278, 2024). "Here, we reasoned to explored the function of HDAC7 in ovarian cancer progression and found that inhibition of HDAC7 obviously cut down p‐AKT and p‐mTOR phosphorylation levels and induced a low rate of cell proliferation and invasion." (PMID 39431349, 2024). "Taken together, these novel findings suggested that inhibition of HDAC7 suppressed ovarian cancer cell proliferation, colony formation and invasion by reducing phosphorylation levels of AKT/mTOR in vitro." (PMID 39431349, 2024). "Similar findings have emerged in studies of testicular cancer, ovarian cancer, and cervical cancer, in which autophagy inhibition confers CDDP sensitivity through mTOR activation." (PMID 38560690, 2024). "In conclusion, we elucidated the underlying molecular mechanism of HDAC7 in the progression of ovarian cancer growth via enhancing the levels of p‐AKT and p‐mTOR." (PMID 39431349, 2024). "Then, we transfected ovarian cancer cells (SKOV3 and A2780) with lentivirus plasmids and detected the expression of PI3K, Akt and mTOR at the protein and phosphorylation levels through WB assays." (PMID 38345576, 2024). "The collaborative action of XTP8 and CALD1 activates the AKT/AMPK/mTOR pathway, regulating EMT to promote ovarian cancer progression." (PMID 38717641, 2024). "PBK promotes autophagy in ovarian cancer cells by phosphorylating ERK1/2 and thereby activating the mTOR pathway while increasing cisplatin resistance." (PMID 38460944, 2024). "Gynecologic cancers, such as endometrial cancer (EC), ovarian cancer (OC), and cervical cancer (CC), are frequently characterized by the dysregulation of the PI3K, AKT, and mTOR (PAM) pathway." (PMID 39456616, 2024). "Collectively, these data provide strong evidences and new sights that HDAC7 controls ovarian cancer cell proliferation and invasion by regulating AKT/mTOR pathway." (PMID 39431349, 2024). "SH3PXD2A forms a complex with ULK1 and MTOR, and the ULK1-SH3PXD2a-MMP14 axis upregulates the aggressiveness of ovarian cancer." (PMID 38903532, 2024). "In ITGB2- silenced ovarian cancer cells (A2780), the protein levels of PI3K (pi-PI3K), AKT (pi-AKT) and mTOR (pi-mTOR) decreased significantly, and the overexpression of PI3K and AKT reversed this change." (PMID 38345576, 2024).
ovarian carcinoma (continued). "CADM1 overexpression potentially inhibits the migration and invasion of ovarian cancer cells by regulating the upstream regulatory factor C4b-binding protein (C4BPA) and the PI3/Akt/mTOR signaling pathway." (PMID 38481252, 2024). "In the present study, we compared two types of ovarian cancer cells, A2780 and SKOV3, using the dual PI3K/mTOR inhibitor, PKI-402." (PMID 38238825, 2024). "In ovarian cancer, increased ROS production and activation of the AKT/mammalian target of rapamycin (mTOR) signaling pathway were involved in the upregulation of SREBP1 and SREBP2, which promoted cell growth and metastasis." (PMID 39103344, 2024). "In the realm of ovarian cancer research, the involvement of the PI3K/AKT/mTOR signaling axis in anti-anoikis resistance has been unraveled, yet its role in liver cancer remains unexplored." (PMID 39066845, 2024). "Collectively, results of the present study demonstrated that baicalein improves the sensitivity of ovarian cancer cells to cisplatin via inhibiting CirSLC7A6/miR-2682-5p/SLC7A6, and further inactivating PI3K/Akt/mTOR and Erk/p38 MAPK pathways." (PMID 37940982, 2023). "Results of previous studies have demonstrated that the PI3K/Akt/mTOR and MAPK pathways in ovarian cancer affect cell metastasis through regulating the expression of E-cadherin, CAM, MMP and tumor angiogenic factors." (PMID 37940982, 2023). "Overexpression of MOB1A has a positive effect on ovarian cancer progression and is likely involved in the regulation of the PI3K/AKT/mTOR signaling pathway." (PMID 37314589, 2023). "The restoration of miR-199a-5p expression in ovarian cancer cells has been shown to increase sensitivity to cisplatin through targeting both mTOR and CD44, thereby reducing ovarian cancer stem cell levels." (PMID 37835506, 2023). "On exploring the intricate cellular mechanics governing ovarian cancer, a recurrent theme emerges: the centrality of the PI3K/Akt/mTOR signaling pathway." (PMID 38239204, 2023). "A recent study showed that JFD improves the efficacy of cisplatin therapy in ovarian cancer and activates NF-κB signaling by suppressing the PI3K/AKT/mTOR axis." (PMID 38104091, 2023). "LINC02489 interacts with PKNOX2 through the PTEN/mTOR axis to reduce the migration and invasion of chemotherapy-resistant SKOV3 cells, thereby increasing the sensitivity of ovarian cancer to paclitaxel." (PMID 37047747, 2023). "Western blotting analysis showed that TTK, mTOR, AKT were highly expressed in ovarian cancer (P < 0.05)." (PMID 36849137, 2023). "Chemoresistant ovarian cancer cells exhibited increased GALNT14 expression, which led to enhanced tumor cell viability via the EGFR/mTOR signaling pathway." (PMID 37671061, 2023). "In approximately 70% of cases of ovarian cancer, PI3K/AKT/mTOR pathways have been shown to be constitutively triggered by autophagy, which has been considered to be a therapeutic target of ovarian cancer." (PMID 35203301, 2022). "Inactivation of PI3K/Akt/mTOR pathway can reverse EMT and inhibit cancer stem cell markers to overcome ovarian cancer chemoresistance." (PMID 35739532, 2022). "This study aims to provide a comparison of the antiproliferative effect of PI3K/AKT/mTOR and RAS/RAF/MEK/ERK pathway inhibitors in 2D monolayer and 3D ovarian cancer models." (PMID 35053555, 2022). "Regulation of C4BPA can inhibit the PI3K/Akt/mTOR signaling pathway induced by the overexpression of CADM1, thereby affecting the migration and invasion of ovarian cancer cells." (PMID 36177001, 2022). "The RAS/MEK/ERK and PI3K/AKT/mTOR signaling cascades converging at BAD participate in maintaining cell survival following both cisplatin and paclitaxel treatment in ovarian cancer." (PMID 35791346, 2022). "Another study found that MHY2245 induces autophagy in human ovarian cancer cells and inhibits energy metabolism through the PKM2/mTOR pathway." (PMID 35163511, 2022).
ovarian carcinoma (continued). "Given that NANOG expression stimulates ovarian cancer cell invasion and migration, we subsequently explored the AMPK/mTOR signalling pathway, which plays an important role in tumour development and metastasis." (PMID 36114703, 2022). "It was found that matrine exerts antitumor effects in drug-resistant ovarian cancer cells in vitro and in vivo by downregulating MAPK/ERK, PI3K/Akt, and Akt/mTOR signaling." (PMID 35684449, 2022). "The mTOR inhibitor rapamycin can strongly inhibit the phosphorylation of S6 and the expression of GLS, and Gln promotes the proliferation of ovarian cancer cells through the mTOR/S6 pathway." (PMID 36523985, 2022). "The mechanisms inducing growth arrest are increased stability of p21 and phosphorylation at Ser130, whereas autophagy induction involves the inhibition of PI3K/Akt/mTOR signaling in A549 cells, and the activation of p38 MAPK/JNK in human ovarian cancer cells." (PMID 35684449, 2022). "In ovarian cancer, the stimulation of tumor cell proliferation via the MAPK/ERK1/2/mTor pathway induced autophagy." (PMID 35860020, 2022). "The down regulation of GALNT14, which is up-regulated in ovarian cancer, inhibits the activity of mTOR pathway through O-glycosylation of EGFR, thereby inhibiting ferroptosis in ovarian cancer cells." (PMID 35784729, 2022). "In the present study the combination of a PI3K/mTOR inhibitor with an ERK inhibitor is shown to have a synergistic effect against both monolayer and three-dimensional ovarian cancer models." (PMID 35053555, 2022). "Treatment with the mTOR activator MHY1485 activated the PI3K-AKT pathway and significantly restored the proliferative and invasive ability of ovarian cancer cells." (PMID 36088429, 2022). "Chemotherapy-resistant epithelial ovarian cancer cells exhibit EMT and increased expression of tumor stem cell markers due to stimulation of the PI3K/Akt/mTOR signaling pathway." (PMID 35402264, 2022). "In this study, the efficacy of combined PI3K/mTOR (BEZ235) and ERK inhibition (SCH772984) was investigated in four human ovarian cancer cell lines, grown as monolayer and three-dimensional cell aggregates." (PMID 35053555, 2022). "In ovarian cancer cell lines, dasatinib initiated autophagic cell death and decreased cell growth in an AKT, mTOR and Beclin 1-dependent manner." (PMID 35392170, 2022). "Another study showed that the dual PI3K/mTOR inhibitor NVP-BEZ235 downregulated Mcl-1 and thereby inhibited the growth of ovarian cancer cells." (PMID 35783514, 2022). "In a study performed using ovarian cancer cell lines OVCAR5 and SKOV3 in vitro, IGF-1 was shown to inhibit E-cadherin expression via the PI3K/Akt/mTOR signaling pathway." (PMID 35565396, 2022). "MiR-582-3p inhibits ovarian cancer survival and migration by targeting AKT/MTOR signaling via lncRNA TUG1." (PMID 35386287, 2022). "Furthermore, UBE2S might accelerate the cell cycle and inhibit apoptosis by promoting PI3K/AKT/mTOR and ultimately drive the malignant biological behavior of OV cells, which may provide new ideas for prognostic evaluation and molecular therapy of ovarian cancer." (PMID 35658829, 2022). "This was unexpected as in ovarian cancer cells dasatinib increased autophagy through a mechanism involving the decreased phosphorylation of AKT, mTOR, p70S6K, and S6." (PMID 35392170, 2022). "This study presents the novel combination of a PI3K/mTOR inhibitor and an ERK inhibitor as a potential treatment for ovarian cancer and directly compares the effect of these inhibitors in both monolayer and three-dimensional in vitro ovarian cancer models." (PMID 35053555, 2022).